EGFR (epidermal growth factor receptor)
Diseases named in the same sentence as EGFR in open-access papers (continued):
Sharing a sentence is not in itself a finding about the gene and the disease.
colon carcinoma (continued). "Furthermore, elevated AREG expression associates with tumor budding, invasion, poor prognosis, and increased sensitivity to EGFR inhibition in HNSCC, while TGFα can confer cetuximab resistance through inducing EGFR-MET interaction in colon cancer." (PMID 41115375, 2025). "Notably, pyrotinib has been reported to induce apoptosis in colon cancer and oral squamous cell carcinoma by targeting EGFR, underscoring its broader therapeutic relevance." (PMID 40830980, 2025). "For instance, anti-EGFR aptamers attached to Au-NPs may target EGFR expressing tumor cells in lung, head, neck, and colon cancers." (PMID 40688030, 2025). "Additionally, the EGFR inhibitor Sapitinib can significantly strengthen the effectiveness of paclitaxel and doxorubicin in colon cancer and overcome resistance." (PMID 40901678, 2025). "Conclusions:rTBL-1 induces apoptosis in colon cancer cells by EGFR independent mechanisms, although its presence could be related to deeper responses." (PMID 40006027, 2025). "Similarly, secondary EGFR mutations in the outer structural domain S492R lead to cetuximab resistance by preventing EGFR antibodies from binding to their target sites in colon cancer." (PMID 38572428, 2024). "Additionally, PRMT1 enhances the transcriptional activity of EGFR, further fostering colon cancer cell proliferation, clonogenicity, and migration." (PMID 38326807, 2024). "In addition, gallic acid inhibits EGFR tyrosine phosphorylation in non-small cell lung and colon cancer cells." (PMID 39063200, 2024). "However, more precise cellular targets have also been recognized; for instance, plantaricin was observed to exert an antiproliferative effect on colon cancer cells by triggering EGFR." (PMID 38792153, 2024). "Consequently, the outcomes of the study imply that ephrinA5 inhibits the progression of colon cancer by promoting the degradation of EGFR as mediated by c-CBL." (PMID 39130630, 2024). "The interaction between EGFR and integrins in colon cancer can promote cell anoikis resistance." (PMID 39199664, 2024). "Furthermore, anti-EGFR monoclonal antibody induces the internalization of EGFR into lysosomes, leading to subsequent lysosomal degradation of the receptors, as observed in colon cancer cells." (PMID 39596025, 2024). "For example, TFF1 promoted anchorage-independent growth in colon carcinoma cells, phosphoinositide 3-kinases (PI3K) dependent migration and invasion in gastric carcinoma cells, and cyclooxygenase-2 (COX-2) and EGF receptor (EGFR)-dependent angiogenesis in kidney and colonic cancer cells." (PMID 39410561, 2024). "Furthermore, the positive staining of tumour cells by the antibody targeting EGFR, highly expressed in colon cancer cells, validated the presence and location of tumour cells in the tissue." (PMID 38553551, 2024). "Furthermore, OLN reduced the expression of GRP78 as well as the viability of human colon cancer cells resistant to an anti-EGFR targeted therapy, Cetuximab." (PMID 39238058, 2024). "Notably, EGFR antibody has been approved as first-line treatment option for KRAS wild-type, EGFR-overexpressing colon cancer patients." (PMID 38961535, 2024). "HB-EGF or EGFR KD enhanced miR-126 and impaired miR-221 expression in colon cancer cells." (PMID 39419989, 2024). "Increased EGFR expression has been shown in adenomas and colon cancer in human and animal studies." (PMID 38609520, 2024). "For instance, C1GALT1 expression was reported to be required for fibroblast growth factor receptor phosphorylation through O-glycosylation in colon cancer tissue and for binding of epidermal growth factor to its receptor (EGFR) through EGFR O-glycosylation in head and neck cancer." (PMID 38622340, 2024). "This work aimed to determine whether rTBL-1 retained its bioactive properties and if its apoptotic effect was related to EGFR pathways by studying its cytotoxic effect on colon cancer cells." (PMID 37259433, 2023). "EGFR is a tyrosine kinase receptor used in targeted colon cancer therapy." (PMID 37259433, 2023).
colon carcinoma (continued). "The current study showed that FOXD3 gene knockout could significantly activate the EGFR-RAS-Raf-MEK-ERK signaling pathway in human colon cancer bone metastatic cells." (PMID 37151068, 2023). "Studies have shown that EGFR is overexpressed in the early stage of colon cancer." (PMID 37564983, 2023). "In colon cancer patients, pharmaceutical antineoplastic expenditure in 2019 included monoclonal anti-EGFR antibodies (53.78%), anti-angiogenic agents (31.92%), BRAF-MEK inhibitors (7.35%), the multi-kinase inhibitor regorafenib (1.19%), and cytotoxic agents (4.57%)." (PMID 37754495, 2023). "In colon cancer, EGFR has a positive association with female survival compared to a negative one in males, suggesting interplay between EGFR and ERβ between the sexes." (PMID 36826068, 2023). "In human colon cancer cell lines and organoids of normal human colonic primary cells, inhibiting epidermal growth factor receptor (EGFR) increased the expression of hBD-1, whilst activating EGFR through the MAPK kinase 1/2 (MEKK1/2)-ERK1/2 pathway had the opposite effect." (PMID 36982340, 2023). "Determining expression levels of both CHRM3 and EGFR in tumor tissue obtained from individuals with colon cancer might enlighten in vivo reflections and importance of our results." (PMID 36919835, 2023). "Fisetin inhibits colon cancer cells by suppressing COx2 and Wnt/EGFR/NF-kappaB signaling pathways." (PMID 37240765, 2023). "The mean expression of EGFR was extremely high (10.7 binary log units), ranking above the 90th percentile of all genes among the 411 specimens of colon cancer without MMR mutations in TCGA." (PMID 37190308, 2023). "Here, we used two-colour single-molecule total internal reflection fluorescence (TIRF) microscopy for super-resolved single-molecule localization microscopy (SMLM) on live human colon carcinoma cells stably expressing EGFR–GFP in the presence of tetramethylrhodamine (TMR) conjugated to EGF." (PMID 35612280, 2022). "Thus, 1,25-(OH)2D3 decreases the expression of epidermal growth factor receptor (EGFR) and promotes its ligand-induced internalization in colon carcinoma cells." (PMID 35406059, 2022). "Interestingly, LciBL23-MVs were able to induce the phosphorylation of epidermal growth factor receptor (EGFR) in the human colon carcinoma cell line T84, showing an effect similar to purified p40 and p75." (PMID 36558455, 2022). "However, targeting the VEGFR and EGFR pathway in cancer vasculature with anti-neovascular therapy offers a new plan for colon cancer treatment." (PMID 35402265, 2022). "This evidence suggests that RP may play a role in the treatment of colon cancer by downregulating EGFR protein expression." (PMID 35260672, 2022). "Three CDx devices, Cobas EGFR Mutation Test V2, ONCO/Reveal Diagnostic Lung and Colon Cancer Assay, and FoundationOne CDx all received approval for therapeutic class labeling following the finalization and release of the April 2020 guidance reiterating the FDA’s position." (PMID 35689144, 2022). "Epidermal growth factor receptor (EGFR) is commonly overexpressed on many types of epithelial malignancies, including lung, kidney, and colon cancers; however, it is also expressed on healthy tissue, leading to an increase in the chances for “on-target, off-tumour” effects." (PMID 35205725, 2022). "Fibroblast growth factor 9 (FGF9) plays a critical role in patients with colon cancer with resistance to epidermal growth factor receptor (EGFR)-targeted therapy, and combination therapy with anti-EGFR inhibitor may reverse drug resistance." (PMID 36221049, 2022). "EGFR is a known regulator of colon cancer contributing to tumor carcinogenesis and progression." (PMID 36146640, 2022). "It has been shown that the overexpression of VIPR1 in colon cancer may be related to the activation of EGFR, which can lead to poor differentiation of colon cancer, thereby promoting cancer progression." (PMID 36157238, 2022).
colon carcinoma (continued). "Furthermore, colon cancer patients who responded (n = 19) to antibody‐based EGFR inhibition therapy (cetuximab) had significantly higher cancer tissue expression of ECAD (IHC scoring) than patients not responding (n = 17) to treatment." (PMID 34890102, 2022). "Curcumin downregulates EGFR in colon cancer cells by reducing the transcription factor EGR194." (PMID 35977996, 2022). "Bile acids could induce proliferation of rat hepatic stellate cells or human colon cancer cell line via activation of the epidermal growth factor receptor." (PMID 35285172, 2022). "Furthermore, PGE2 treatment of normal gastric epithelial and colon cancer cells led to an activation of EGFR and ERK." (PMID 35804847, 2022). "It has also been found that DCA can promote the transcription of MUC2 mucin in HM3 colon cancer cells by active ting multiple pathways, including the EGFR/PKC/Ras/rf-1/MEK1/ERK/CREB, PI3K/Akt/IkappaB/NF-B and p38/MSK1/CREB pathways, and this effect can be inhibited by the erJNK/c-jun/ap-1 pathway." (PMID 35574393, 2022). "We provided evidence that colon cancer patients harboring the BRAF(V600E) oncogenic mutation were lack a significant response to PLX4720, but BRAF and EGFR inhibition can be synergistic when combined, suggesting more combining targeted agents can be used in clinical trials." (PMID 35652270, 2022). "All KRAS mutant colon cancer models were insensitive to EGFR inhibition." (PMID 35368031, 2022). "Recently, the EGFR-targeting monoclonal antibody cetuximab has been administered to colon cancer patients without KRAS mutations." (PMID 35110666, 2022). "Thus, BA-induced colon cancer cell proliferation is M3R-dependent and mediated, in part, by transactivation of EGFR." (PMID 33450835, 2021). "Moreover, the co-administration of curcumin and 5-FU and oxaliplatin significantly suppressed EGFR signalling via the increased methylation status of EGFR, emphasizing the role of curcumin in the epigenetic modulation of colon cancer cells." (PMID 34299604, 2021). "Moreover, another research unveiled that p38 MAPK confers intrinsic resistance to EGFR TKIs, lapatinib and gefitinib, in K-Ras mutant colon cancer cell lines, by concurrent stimulation of EGFR gene transcription and protein dephosphorylation." (PMID 34943871, 2021). "This P(3HB-3HHx) NP was wholly biofunctionalized using the PHA granule-associated protein PhaP fused to an Epidermal Growth Factor Receptor (EGFR)-targeting peptide and tested for their enhanced cellular uptake in human colon cancer cell lines as well tumor targeting ability in vivo." (PMID 33959586, 2021). "This suggests that episamarcandin may play a role in colon cancer HCT 116 cells in an EGFR independent way." (PMID 34765011, 2021). "Moreover, cell line experiments exhibited increased PVT1 levels in HT29 colon spheres compared with their parental counterparts along with increased VEGFA and EGFR levels, the two major metastatic or oncogenic markers in colon cancer." (PMID 34336125, 2021). "These genes have been shown to play a role in colon cancer development and may thus provide the cell with some growth advantage under anti-EGFR therapy, supporting resistance development." (PMID 34271981, 2021). "The phosphorylation status of transphosphorylation site Y845 of the receptor tyrosine kinase (RTK), EGFR, a site noted for its activation by Src was also significantly decreased in adjacent normal (P = 0.003) and colon tumor (P = 0.01) samples taken from Anthos–treated animals over control animals." (PMID 34926717, 2021). "Furthermore, in patients with mCRC treated with anti-EGFR agents, a higher overall response rate is achieved in left-sided colon tumours than in rectal tumours." (PMID 34188197, 2021). "EGFR-PKC-CLDN1 pathway suggested as a tumorigenic pathway in colon cancer cells." (PMID 33597819, 2021).
colon carcinoma (continued). "PI3K-Akt-mTOR signaling pathway is one of two downstream signaling pathways of EGFR, which can promote colon cancer cell proliferation, prolong cell survival, inhibit cell apoptosis, and participate in angiogenesis, leading to invasion and metastasis of colon cancer." (PMID 34765011, 2021). "Moreover, colon cancer mediates tumorigenesis through several molecular pathways, such as the overexpression of epidermal growth factor receptor (EGFR) family members." (PMID 33796026, 2021). "Therefore, the knockout of EGFR by siRNA has been considered a potential strategy for the treatment of colon cancer." (PMID 33796026, 2021). "Anti-EGFR antibodies are the most common targeted therapy used in the treatment of colon cancer." (PMID 34885111, 2021). "In clinical practice, during our multidisciplinary team meetings, middle/low rectal cancer was noted to be refractory to anti-EGFR therapy to some extent, and the efficacy of this therapy for middle/low rectal cancer was below expectations compared to left-sided colon cancer." (PMID 34188197, 2021). "In addition, chrysophanol represses cell proliferation of colon cancer via epidermal growth factor receptor (EGFR)/ mammalian target of rapamycin (mTOR) signaling proteins such as extracellular signal-regulated kinase 1/2 (ERK1/2), P70S6K and AKT." (PMID 34519612, 2021). "Notably, EGFR and VEGF mutations are often determined to be associated with increased metastatic incidence and poor prognosis in colon cancer." (PMID 34336125, 2021). "As colon cancers express high levels of activated EGFR, a combined blockade of EGFR and BRAF or even downstream MEK may work synergistically and could be a potential therapeutic opportunity in CRC." (PMID 34885128, 2021). "EGFR has also previously been shown to elevate LD numbers in human colon cancer cells." (PMID 34262037, 2021). "Indeed, tumor YAP expression is positively correlated with the survival rate of colon cancer patients, and epidermal growth factor receptor (EGFR)/YAP signaling plays a critical role in promoting 5-FU resistance." (PMID 33467099, 2021). "EGFR contributes to malignant behaviors of colon cancer cells in five ways—transformation of non-tumorigenic cells into tumorigenic cells, mitogenesis of polarizing colon cancer cells, cancer cells proliferation, cellular metastasis, and autophagy." (PMID 34638601, 2021). "In the colon carcinoma cell lines with high EpCAM expression levels, the initial stimulation provided by the bispecific antibody was efficiently enhanced by all three costimulatory fusion proteins targeted to highly and moderately expressed EGFR." (PMID 32504247, 2020). "This protein is a ligand of EGFR and promotes proliferation in ovarian and colon cancer models." (PMID 32552913, 2020). "Likewise, the miR-27a/ZBTB10/Sp/EGFR axis was also observed in colon cancer cells after treatment with ethyl 2-((2,3-bis(nitrooxy)propyl)disulfanyl)benzoate (GT-094, a novel nitric oxide chimera that induces ROS production)." (PMID 35006436, 2020). "PD-L1 and EGFR interact in colon cancer cells, and their combination in GCa may influence their sensitivity to TRAIL." (PMID 32775300, 2020). "EGFR expression in colon cancer was used as a positive control." (PMID 32833992, 2020). "In a recent study, EGFR was overexpressed in 60–80% of colon cancers." (PMID 32149326, 2020). "However, this is unlikely as both the parental and MDR colon cancer cell lines have similar expression levels of EGFR." (PMID 33158067, 2020). "Activation of EGFR results in unresponsiveness of colon cancer to BRAF(V600E) inhibition." (PMID 31896739, 2020).
colon carcinoma (continued). "Because PP2 also reduced EGFR phosphorylation, we suggest there is a feedback loop to control EGFR activation through SFKs as previously reported in fibroblasts, breast, and colon cancer cells in a transactivation manner." (PMID 32093123, 2020). "In colon cancer, the expression levels of this receptor are higher, and BRAF inhibition causes a relief of the regulatory loop, resulting in pathway rebound induced by upstream EGFR activation." (PMID 33291749, 2020). "The KEGG pathway analysis suggested that the inferred functions of the top lncRNAs were involved in the apoptosis signaling pathway, PI3K-AKT pathway, EGFR pathway, colon cancer pathway, and platinum drug resistance, which are fundamental processes for colon cancer development." (PMID 30984308, 2019). "In addition to traditional chemotherapy, drugs that target EGFR can be used for efficient advanced colon cancer treatment." (PMID 31717759, 2019). "Transactivation of EGFR following M3R activation was demonstrated in H508 human colon cancer cells." (PMID 30841571, 2019). "Collectively, we develop a multifunctional nanoparticle formulation of afatinib and miR-139 with targeting, penetrating, and pH-responsive characteristics for simultaneous modulation of EGFR/HER/Ras/Akt/Rac1/STAT3/MAPK/EMT/Bcl-2 pathways to increase the sensitivity of colon cancer cells to afatinib." (PMID 31426807, 2019). "In addition, vitamin B9 supplementation to HCT116 and Caco-2 colon cancer cell lines reduced TGFβ secretion, induced cancer cell proliferation, and reduced tyrosine kinase activity and epidermal growth factor receptor expression." (PMID 31374832, 2019). "Furthermore, in HER2-amplified LIM1215-HER2 and SW48-HER2 colon cancer cells HER2 activation was accompanied by the interaction of HER2 with both EGFR and HER3, respectively, by forming HER2/EGFR and HER2/HER3 complexes." (PMID 31164152, 2019). "EGFR signaling is yet another key pathway linking colon cancer and claudin-2." (PMID 31726679, 2019). "Anticancer activity of tephrosin may be implemented through the induction of epidermal growth factor receptor (EGFR) and ErbB2 internalization and degradation of colon cancer cells as well as autophagic cell death." (PMID 31814840, 2019). "The colon cancer cells responding to TGFα ligand were determined by DNA sequencing to harbor oncogenic mutations (KRASG13D and BRAFwt in CC36; KRASwt and BRAFV600E in CC14, KRASG12D, and BRAFwt in LS174T) downstream of the TGFα receptor EGFR." (PMID 31253868, 2019). "However, emerging evidence suggests that treatment of colon cancer patients with anti-EGFR agents increases intra-tumor heterogeneity, leading to the emergence of clones with different genetic alterations." (PMID 31740709, 2019). "Diminished clonogenic survival and increased numbers of γH2AX foci in HCT116 colon cancer cells were observed by media transfer experiments following exposure of donor cells to 125I-labelled anti-epidermal growth factor receptor (EGFR) monoclonal antibodies (mAb)." (PMID 31659527, 2019). "15-PGDH has been shown to be reactivated in colon cancer cell lines by inhibiting EGFR signaling." (PMID 30931980, 2019). "We presented a dual-targeting nanomedicine approach for cancer therapy using MGO-PEG-CET/DOX that combines co-precipitated Fe3O4 magnetic nanoparticles and CET (an EGFR antibody) for magnetic and receptor-mediated ligand-targeting of malignant CT-26 mouse colon carcinoma." (PMID 29584656, 2018). "Collectively, Src can play a key role in apoptosis induced by the novel EGFR inhibitor MHYs, suggesting that activation of Src might prove effective in treating EGFR/wild-type KRAS colon cancer." (PMID 30158525, 2018). "Subgroup analysis showed a positive prognostic impact of starting CT plus anti-EGFR in left colon cancer (pooled HR: 0.70; CI: 0.54–0.85) while a positive trend of starting CT plus bevacizumab was observed in right colon cancer (pooled HR: 1.29; CI: 0.81–1.77)." (PMID 29773991, 2018).